IL1B (interleukin 1 beta)
Diseases named in the same sentence as IL1B in open-access papers (continued):
Sharing a sentence is not in itself a finding about the gene and the disease.
depression (continued). "Mounting studies reveal that both IL-1β and IL-6 are important in the etiology and pathophysiology of depression." (PMID 23596475, 2013). "This later finding is important as it illustrates that IL-1β activity within the brain is required for the development of depression-like behavior." (PMID 23634700, 2013). "Chronic mild stress (CMS) of mice not only elevates IL-1β levels but also results in depression-like symptoms, including a decrease in sucrose preference (to the point of aversion) and decreased social exploration." (PMID 23634700, 2013). "In depression there is an increase in pro-inflammatory cytokines (interleukine-1β (IL- 1β); IL-6, and IFNγ (interferon-gamma)) and the acute phase of depression is due to high levels of pro-inflammatory cytokines such as IL-6 and IL-1β." (PMID 23204984, 2012). "IL-1β, which clinically correlates with elevated ICP after TBI, is implicated in the pathophysiology of depression and anxiety and in neuronal cell death and cognitive dysfunction after experimental TBI." (PMID 22815977, 2012). "A cluster of cytokines including interleukin-1 beta (IL-1β), IL-2, IL-6, interferon-gamma, and tumor necrosis factor alpha (TNFα) have been reported to correlate with depression symptoms." (PMID 21864357, 2011). "Recent studies have provided several lines of evidence implicating the pro-inflammatory cytokine interleukin-1beta (IL-1β) in the etiology and pathophysiology of depression." (PMID 21726461, 2011). "Activation of the innate immune system of the brain contributes to pathophysiologic changes that occur in depression due to the generation of inflammatory mediators including nitric oxide, via iNOS, and pro-inflammatory cytokines such as IL-1β and TNFα." (PMID 21306618, 2011). "This evidence suggests that genetic regulation of inflammatory processes mediated by IL-1β is involved in the pathophysiology of depression and resistance to antidepressant treatment." (PMID 21726461, 2011). "Concerning the immunological mechanisms, certain pro-inflammatory cytokines, mainly IL-6, IL-1β and TNFα, have been recently pointed out as pivotal molecules for depression-related behaviors following infection." (PMID 21194425, 2010). "Intriguingly, cytokines like IL-1β are suggested to be involved in the pathophysiology of depression." (PMID 20029634, 2009). "The results of western blot confirmed that administration of DSCG could attenuate LPS‐induced upregulation of ASC, pro‐caspase‐1, and pro‐IL‐1β in the brain from depression model mice." (PMID 41556446, 2026). "Additionally, JAK–STAT pathway activation drives microglial transformation to a proinflammatory phenotype (M1 phenotype), releasing IL-1β, ROS and activating other signalling pathways, thus contributing to depression (Ref." (PMID 40905280, 2025). "The present study aims to assess and compare the serum concentrations of BDNF and IL-1β in individuals with depression, helping to identify potential biomarkers that could predict disease progression and responses to treatment." (PMID 40904969, 2025). "Furthermore, limonene improved depression in maternally separated mice and reduced neuroinflammation by lowering hippocampal nitrite levels and the expression of IL-1β and TNF-α." (PMID 40443223, 2025). "In addition to these neurotrophic factors, some cytokines have been highlighted within the clinical picture of depression, with some being studied as potential biomarkers for this disorder, such as IL‐1β and IL‐10." (PMID 41030588, 2025). "Elevated cytokines such as IL-10, IL-1β, and TNF-α are linked to common comorbidities of depression, including hypertension and diabetes, and may serve as potential markers of disease severity and treatment response." (PMID 41226736, 2025).
depression (continued). "In patients with IBD comorbid with depression, microglia are often in the M1 state, leading to the excessive release of pro‐inflammatory factors such as IL‐1β and tumor necrosis factor α, which further exacerbate central nervous system inflammation and trigger depressive symptoms." (PMID 40823702, 2025). "Thus, our findings provide insight into the key therapeutic effect of COS and novel molecular mechanism of microglial Akt/mTOR/NF-κB/IL-1β signaling pathway for the treatment of major depression." (PMID 40011631, 2025). "Patients with depression often exhibit increased levels of interleukin-6 (IL-6), IL-1β, IL-10, tumour necrosis factor-α (TNF-α), CRP, and transforming growth factor-β (TGF-β), many of which are produced in response to cellular stress through inflammasome activation." (PMID 41226736, 2025). "Contradictory to many past studies, we showed a downregulation of IL-1β in depression patients." (PMID 40179065, 2025). "It has been mentioned in many studies related to the pathogenesis of depression that the activation of microglial in the prefrontal cortex or hippocampus and the release of pro-inflammatory factors such as IL-1β, TNF-α and IL-6 in depressed animals with stress models." (PMID 40336842, 2025). "Available research demonstrates that schizophrenia and depression both have shown increased rates of cytokines, including IL-1β, IL-6, and TNF-α, which indicate systemic inflammation followed by cognitive impairment, treatment unresponsiveness, and disturbances in mood." (PMID 40416228, 2025). "One hypothesis suggests that gut dysbiosis may contribute to enhanced cytokines release (e.g., IL-1β, IL-6, TNF-α), resulting in a higher activation of the HPA axis and enhancing the risk of developing symptoms of anxiety and depression in IBD." (PMID 39870972, 2025). "Elevated expression of tumor necrosis factor-α (TNF-α), interleukin-1β (IL-1β), interleukin-6 (IL-6), and nuclear factor kappa B (NF-κB) signaling have been identified in patients with depression and replicated in animal models of high-fat diet (HFD) and stress-induced behavioral despair." (PMID 40558565, 2025). "In addition, qPCR analysis showed an upregulation in the expression of inflammatory markers like IL‐1β, TNF‐α, and the depression‐associated gene SLC6A4 after hormonal treatment and TBI exposure." (PMID 39665190, 2025). "Elevated levels of cytokines such as TNF-α, IL-1β, and IL-6 may exacerbate neuroinflammatory responses, with their concentrations positively correlating with the severity of depression." (PMID 40427467, 2025). "According to evidence, increasing levels of inflammatory markers such as IL-1β, IL-6, and TNF-α may be associated with depression." (PMID 40487411, 2025). "The findings indicated that the isolated mice displayed clear signs of anxiety and depression-like behaviors, along with increased levels of various cytokines (IL-1β, IL-6, and TNF-α) in the hippocampus and decreased levels of Sirt1, accompanied by elevated NF-κB p65 expression." (PMID 41317200, 2025). "In addition, it has been reported that chronic pain can autonomously contribute to the pathogenesis of depression by increasing the level/expression of proinflammatory cytokines such as IL-1β, IL-6, and tumor necrosis factor α (TNF-α)." (PMID 40225229, 2025). "Decreased IL-1β and increased IL-6 may act as a compensatory mechanism in depression to counter act dysregulated neuroinflammatory response." (PMID 40179065, 2025). "In the pathophysiology of depression, IL-1β synergistically contributes to central 5-HT system hypofunction: it activates IDO1, diverting Trp metabolism away from 5-HT synthesis, and upregulates the SERT to accelerate the clearance of 5-HT from the synaptic cleft." (PMID 40641625, 2025).
depression (continued). "In our review, we noticed that IL-1β decreased with the administration of the SSRIs escitalopram (one study) and fluoxetine (three studies) in patients with depression, as well as with ketamine (one study in patients with treatment-resistant depression)." (PMID 40573262, 2025). "Notably, microbiome transplantation in depression models and probiotic interventions in Parkinson’s disease have been shown to reduce pro-inflammatory cytokines (e.g., IL-1β, TNF-α) and normalize microglial activity." (PMID 40371088, 2025). "Our findings indicate that acupuncture reduces TNF-α and IL-1β levels in the brain tissue of depression animals; it may be due to the fact that acupuncture can regulate inflammatory cell signaling pathways." (PMID 41244868, 2025). "TENS can reduce serum IL-1β and IL-6 concentrations in patients with late-pregnancy depression." (PMID 40904577, 2025). "Rhein’s strong effect on IL-1β suggests it may have particular value in treating inflammation-driven depression." (PMID 40487411, 2025). "The preceding authors believe that IL-1B may be thus used as an indicator for the early diagnosis of patients with depression." (PMID 40313235, 2025). "For every unit (pg/dL) increase in IL-1β, the odds of clinical depression rose by 98%." (PMID 39902492, 2025). "Interestingly, IL-1β antagonists can reverse these behavioral changes, supporting the role of inflammation in depression." (PMID 40277932, 2025). "In this model, depression-like behaviors correlate with the release of pro-inflammatory cytokines, including interleukin 1β (IL1β), interleukin 6 (IL6), and tumor necrosis factor α (TNFα), in both the brain and plasma, thereby establishing a connection between inflammation and depressive symptoms." (PMID 40001487, 2025). "NOD-like receptor of protein 3 (NLRP3) inflammation may be involved in LPS-induced depression-like pathological changes and promote IL-1β secretion and synthesis." (PMID 40520890, 2025). "Moreover, treatment with antidepressants has been found to decrease IL-1β levels in individuals with depression." (PMID 40904969, 2025). "The activation of NLRP3 and the release of IL-1β and IL-18 may be involved in the pathogenesis of depression through multiple mechanisms." (PMID 40497971, 2025). "Additionally, chronic mild stress and other depression models have shown increased levels of pro-inflammatory cytokines like IL-1β, IL-6, TNF-α, and IL-17 in both animals and humans." (PMID 39335629, 2024). "Furthermore, additional investigations have shown increased blood levels of IL-1β, IL-2, and IL-8 in individuals suffering from depression." (PMID 38877455, 2024). "While administration of IL‐1β to the intracerebroventricular area caused depression‐like behavior, it was observed that depression behavior did not occur in mice with IL‐1β receptor deficiency." (PMID 39443283, 2024). "Furthermore, it leads to heightened corticosterone levels and triggers activation of the innate immune system, resulting in elevated inflammatory cytokines (such as IL-6, IL-1β, and TNFα), thus impacting the onset of depression." (PMID 38680928, 2024). "In a similar vein, patients diagnosed with various forms of depression often show significantly elevated levels of IL-1β in their cerebrospinal fluid (CSF), serum, or urine, as well as higher TNF-α concentrations in their serum, when compared to non-depressed individuals." (PMID 39684342, 2024). "Besides, the facilitative role of brain IL-1β in the pathogenesis of depression has also been revealed, confirming the contribution of central inflammatory cytokines in depression." (PMID 38627830, 2024). "Likewise, in a model of depression induced by corticosterone, an increase in serum levels of IL-6 and IL-1β was found, indicating that inflammatory processes are involved in the development of depressive disorders." (PMID 39585071, 2024). "Minocycline can ameliorate depression by reducing the levels of IL-1β in the hippocampus." (PMID 38459460, 2024).
depression (continued). "Among the various pro‐inflammatory cytokines released during chronic viral hepatitis infection, emerging evidence suggests that IL‐1β may play a pivotal role in the pathogenesis of depression." (PMID 37937732, 2024). "The P2X7R/NLRP3/IL‐1β pathway is an important pathological mechanism of diabetes and depression." (PMID 38752512, 2024). "Since neural damage is associated with inflammation in the course of diabetes, elevated IL-1b levels in the brain may be one of the factors contributing to depression." (PMID 39684343, 2024). "Here we found IL‐1β had predictive effect on middle-term prognosis of depression, which maybe an interventional target or predictive factor." (PMID 38459460, 2024). "Additionally, PAMK decreased anxiety/depression-like behaviors and expression of IL-6, IL-1β, TNF-α, and MCP-1 in the hippocampus." (PMID 39599623, 2024). "On the other hand, in a cross-sectional study conducted in Brazil, an assessment of the relationship between IL-1β and the incidence of depression in older age found higher levels of this pro-inflammatory factor in people with depression compared with controls." (PMID 38575920, 2024). "Notably, IL-1β has emerged as a reliable predictor of IBS-D in the colon and is strongly associated with indicators of pain and depression." (PMID 39006851, 2024). "In addition, the expression levels of TLR4, P65, P-P65, NLRP3, ASC, caspase-1, and IL-1β were elevated in depression models." (PMID 38261756, 2024). "In clinical trials, it has also been found that statin drugs may downregulate IL-1β and NF-κB as anti-inflammatory drugs for the treatment of depression in patients with coronary heart disease." (PMID 38255289, 2024). "Pro-inflammatory cytokines such as TNF-α and IL-1β are pivotal in the neuroinflammatory response observed in LPS models, playing critical roles in the pathogenesis of neurodegenerative and psychiatric disorders, including depression and cognitive impairments." (PMID 39459047, 2024). "It is also vital in the occurrence and development of depression, which can be proven by the facts that the level of IL-1β in cerebrospinal fluid (CSF) or serum of patients with major depressive disorder (MMD) increased, and IL-1β treatment can cause depression-like behavior in rats." (PMID 39408591, 2024). "IL-1β can suppress vitro neurogenesis of human hippocampal progenitor cells, induce synaptic pruning, which leads to impaired neuroplasticity and structural brain changes, both are common in depression." (PMID 38459460, 2024). "Elevated levels of TNF, IL‐6, and IL‐1β in depression may result from dysfunction in the brain's anti‐inflammatory mechanisms, including the HPA axis and noradrenergic innervation." (PMID 38898740, 2024). "It is also possible that although IL-1β is a marker of inflammasome activation, a pathway implicated in depression, it is not the ideal model for depressive inflammation." (PMID 39175522, 2024). "Therefore, the first purpose of this study was to clarify the difference in peripheral RvD1, NLPR3, IL-1β, Il-18, and IL-4 between the adolescent patients with depression and the healthy control group." (PMID 38627683, 2024). "TaVNS can alleviate depression‐like behaviors induced by a high‐fat diet in ZDF rats which might be due to anti‐inflammation by up‐regulation of the P2X7R/NLRP3/IL‐1β signaling pathway in PFC." (PMID 38752512, 2024). "Additionally, we analyzed the primary domains of IL‐1β‐related depressive symptoms according to Beck's six symptom categories of depression." (PMID 37937732, 2024). "Proinflammatory cytokines tumor necrosis factor α (TNF-α), interleukin-1 β (IL-1β), and interleukin-10 (IL-10) are elevated in major depressive disorder and HS, suggesting a possible pathophysiological process for increased inflammatory symptoms in comorbid patients." (PMID 39173146, 2024).
depression (continued). "Furthermore, the dysregulation of serum inflammatory cytokines, such as IL-1β, IL-6, and TNF-α, has been observed in pediatric patients with major depressive disorder (MDD), and it is linked to depression in children with cancer." (PMID 38927907, 2024). "Importantly, increasing the expression of hsa-miR-532-5p in these mice led to a decrease in depression-like behaviors and the suppression of inflammatory markers like IL-6, IL-1β, TNF-α, and MCP-1." (PMID 39451524, 2024). "EA downregulated the expression of P2X7R/NLRP3/IL-1β and relieved depression-like behavior." (PMID 39367470, 2024). "In addition, chemogenetic silencing of IL‐1β, proinflammation cytokine that is highly active during oxidative stress and depression, significantly attenuates anxiety‐ and depression‐like behaviors in mice exposed to LPS." (PMID 36573693, 2023). "In the present study, we found that maternal separation led to anxiety- and depression-like behaviors in offspring, the upregulation of the hippocampal levels of pro-inflammatory cytokines (IL-1β, IL-6, and TNF-α), and the inhibition of the Sirt1/NF-κB signaling pathway." (PMID 37273278, 2023). "IL-1β cytokines have a role in stress responses and depression." (PMID 37252156, 2023). "On the other side, there is another study demonstrating the association of the TT genotype, not the CC, of IL1B-511C/T with depression." (PMID 37510364, 2023). "In this context, NF-κB has been hypothesized to stimulate the release of inflammatory mediators, including TNF-α, interleukin (IL)-1β, and IL-6, as well as promoting neuroinflammatory processes, finally leading to depression." (PMID 37998350, 2023). "It is well known that IL-1β induces depression-like behaviors by activating the NF-κB pathway." (PMID 36793870, 2023). "Recent studies have identified the involvement of the IL1B gene in depression." (PMID 37510364, 2023). "However, depression severity and the IL-1β level were lower after a 6–8-week treatment by Fluoxetine." (PMID 37009097, 2023). "Furthermore, the antidepressant effects of MLT were found to be related to the modulation of neuroinflammation by regulating hippocampal NF-κB phosphorylation and cytokines (TNFα, IL-1β, and IL-6) in the LPS-induced depression model." (PMID 36747075, 2023). "Although TNF-α, IL-6, and IL-1β play crucial roles as acute phase proteins, they may act differently in the pathology of depression." (PMID 37009013, 2023). "Also, microglia-derived pro-inflammatory factors, such as TNF-α, IL-6, and IL-1β, are proven to be involved in the regulation of depression by modulating neuronal function." (PMID 38023826, 2023). "Moreover, IL-1β was reported to suppress in vitro neurogenesis of human hippocampal progenitor cells, a common finding in depression." (PMID 36331794, 2023). "Regression analysis showed that IL-1β level was negatively correlated to depression severity." (PMID 37009097, 2023). "Moreover, Ferentinos and colleagues reported that depression severity correlated with higher serum levels of IL-1β." (PMID 37252156, 2023). "Studies have confirmed that IL-1β can mediate glutamate overproduction and reduce serotonin reuptake by modulating mitochondria glutaminase activity, which contributes to the progress of depression." (PMID 37600668, 2023). "After binding to the IL-1 type I receptor, IL-1β could mediate the activation of the HPA axis in the rodent model of depression, which provides evidence for IL-1’s role in activating the HPA axis." (PMID 37152963, 2023). "Clinical studies have found that compared with normal people, patients with depression have proinflammatory cytokines such as tumor necrosis factor-α(TNF-α)、Interleukin-1β(IL-1β)、IL-6 and interferon While anti-inflammatory cytokines such as IL-10, IL-4, IL-8 and transforming growth factor." (PMID 37167313, 2023).